CD4 (CD4 molecule)
Diseases named in the same sentence as CD4 in open-access papers (continued):
Sharing a sentence is not in itself a finding about the gene and the disease.
tuberculosis (continued). "Furthermore, dysregulated or excessive CD4+ T cell activation can enhance host susceptibility to Mycobacterium tuberculosis (Mtb) infection; as such, effector T cell responses must be tightly regulated for host survival to TB." (PMID 32218774, 2020). "In a previous study, the addition of urine LAM testing to sputum Xpert reduced mortality in hospital inpatients with HIV with suspected tuberculosis who had a CD4 count of less than 100 cells per μL or severe anaemia, subgroups at highest risk of M tuberculosis BSI." (PMID 32178764, 2020). "The role of CD4/CD8 ratio on the incidence of tuberculosis (TB) in patients on antiretroviral therapy (ART) is unknown." (PMID 32442166, 2020). "Previous tuberculosis, HIV prevalence and CD4 count was similar in all diagnostic outcome groups." (PMID 31931736, 2020). "In this study, we compared the changes in the numbers of CD4 and CD8 T-cells in patients with HIV-negative active tuberculosis (ATB), examined the factors associated with these changes by regression analysis using the optimal scaling method, and further evaluated the degree of correlation." (PMID 32472529, 2020). "Indeed, access to baseline CD4 testing, screening and management of opportunistic (tuberculosis, cryptococcal meningitis) and access to prophylaxis (isoniazid preventive therapy & pre-emptive fluconazole) remains a challenge in the Zimbabwe’s public sector." (PMID 31910445, 2020). "That CD4 T cells protect against tuberculosis by secreting TH1 cytokines is well established." (PMID 31396406, 2019). "Importantly, the vaccine induced robust CD4 T cells against Ag85B, a major component of subunit vaccines against tuberculosis in humans and mice." (PMID 31396406, 2019). "CD4 cell count, clinical staging, body mass index (BMI), not using cotrimoxazole, body weight, and functional status were significant predictors of tuberculosis risk." (PMID 31186628, 2019). "In particular, it has been shown that the A-allele was a risk factor for HIV infection, and that HIV-infected patients with the A-allele had a higher risk of HIV-tuberculosis co-infection, lower CD4+ cell count, and lack of response to ART." (PMID 30611204, 2019). "This is due to savings from preventing opportunistic diseases, such as tuberculosis and bacterial infections, which are the most common complications in Côte d’Ivoire and similar settings in people with higher CD4 counts, as well as preventing HIV transmissions." (PMID 31247009, 2019). "The objective of this study is to characterize the cytokine profile of the CD4+ T cell response to a range of M. tuberculosis-associated antigens, including multiple latency-associated antigens, in patients at the different clinical stages of TB, using multi-parameter flow cytometry." (PMID 31849981, 2019). "With time, the body fails to control the viral replication and immune paresis sets in, being marked by low CD4 counts with increased morbidity and mortality from opportunistic infections with tuberculosis being the most common opportunistic presentation at HIV diagnosis." (PMID 30073038, 2018). "These include a high proportion of co-infections with tuberculosis (23.6%) and other bacterial pathogens (14.3%), very low median CD4 cell counts (26 cells/mm3, IQR 12 to 70), and severe impairment of oxygenation (median PaO2 6.9 kPa, IQR 5.7 to 7.9) at presentation." (PMID 30071089, 2018). "Ongoing HIV replication is an important risk factor for tuberculosis, regardless of CD4 cell counts [7▪], but tuberculosis risk does not differ before and after ART initiation when appropriately controlled for laboratory values and ART exposure [8▪]." (PMID 29698255, 2018). "The findings from this randomised trial suggest that urine-based tuberculosis screening of HIV-positive hospital inpatients might reduce 56-day mortality in defined clinical subgroups (low CD4 count, severe anaemia, or clinically suspected tuberculosis)." (PMID 30032978, 2018).
tuberculosis (continued). "Some of the independent predictors of poor outcomes in patients with HIV-associated tuberculosis from other studies include: age, sex, ambulatory status, WHO clinical stage 4, BMI, lower CD4 count, ART, cotrimoxazole prophylactic therapy, haemoglobin, and white cell count." (PMID 29433509, 2018). "In case of HIIS additional specifications included a CD4+ lymphocyte count ≥200/mm3 and a positive T-cell function (via analyzable positive control of a standard tuberculosis interferon-gamma-release-assay (TB-IGRA) indicating mitogen-induced T cell proliferation)." (PMID 29499726, 2018). "The association between tuberculosis and HIV is also well established and in this study there was strong evidence of an association between having CD4 count < 350 cells/mm3 after 6 months on ART and having a diagnosis of tuberculosis (aOR 8.5, 95% CI 1.1–73.0, p = 0.05)." (PMID 29783953, 2018). "When CD4+ T recovery does not happen, associated comorbidity from opportunistic infections like tuberculosis and life-threatening bacterial infections contribute to mortality." (PMID 30018988, 2018). "Differing CD4 count medians (107 in Schleicher’s cohort compared with 77 × 109 cells/L in ours) tuberculosis versus PJP and CAP versus PJP may account for higher procalcitonin concentrations in our tuberculosis group." (PMID 30107791, 2018). "The child who was treated for active tuberculosis on arrival had a CD4% below 15% (13%)." (PMID 30265670, 2018). "HIV cases whose CD4 count less than 200 were more than nine times likely to develop tuberculosis compared to those whose CD4 count greater than 500 (AOR= 9.04[4.23- 79.11]), besides, a significant statistical relationship was found between smokers and nonsmokers (AOR=4.019[0.01-0.16])." (PMID 29997701, 2018). "A Ugandan study of hospitalized HIV-infected patients presenting with suspected pneumonia of 2 weeks to 6 months duration, most of whom had tuberculosis, found heart rate > 120/min, respiratory rate > 30/min, oxygen saturation < 90%, and CD4 cell count < 50 cells/μL predicted mortality." (PMID 29433509, 2018). "Likewise, a study done in India, opportunistic infections pertaining to the CD4 level among HIV seropositive patients revealed that 17% of prevalence of tuberculosis was observed as soon as the CD4 level reduced below 200/μl." (PMID 29997701, 2018). "For example, the TAM-TB assay, which evaluates the ratio of the median fluorescence intensity of CD27 within the whole CD4+ T-cell population to that of CD27 in the M. tuberculosis–specific IFN-γ+ CD4+ T cells has been shown to distinguish between tuberculosis in LTBI in children and adults." (PMID 28329119, 2017). "Within this cohort, which had a baseline INH monoresistance of 6.1% (low-level resistance associated with inhA) and a significant proportion with advanced immunosuppression (25% with HIV-1 and tuberculosis and a CD4+ T-cell count of <100 cells/mm3), the estimated incidence of ADR was 0.3%–1%." (PMID 28934422, 2017). "Although their exact function remains unclear, CD4+ T cells have been suggested to play a key role in controlling both malaria and tuberculosis." (PMID 28583115, 2017). "Since IP-10 identifies HIV/tuberculosis-infected patients, despite their low CD4 counts, it might be used to monitor for relapses of leishmaniasis in HIV/Leishmania-infected patients." (PMID 28620584, 2017). "Tuberculosis vaccine candidates can elicit polyfunctional CD4+ T cells in the lung." (PMID 29051764, 2017). "Five factors (Male gender (p=0.005), CD4 count <350 cells/mm3, (p=0.035), unknown CD4 count (p=0.048), tuberculosis (p=0.033) and renal failure (p=0.013)) were found to be independently associated with a higher risk of IHM in the logistic regression analysis." (PMID 28533849, 2017). "There is growing evidence that impaired CD4+ T-cell functions play a role in tuberculosis." (PMID 28582466, 2017).
tuberculosis (continued). "One study demonstrated that an innate immune cell subset, myeloid-derived suppressor cells (which are known to suppress CD4+ T-cell function), was significantly increased during both tuberculosis and recently acquired LTBI, compared with treated tuberculosis and remotely acquired LTBI." (PMID 28329119, 2017). "Male gender (p=0.005), CD4 count <350 cells/mm3 (p=0.035), unknown CD4 count (p=0.048), tuberculosis (p=0.033) and renal failure (p=0.013) were independently associated with IHM." (PMID 28533849, 2017). "A significantly lower frequency in missed appointments (14.0% vs 35.5%) (p = 0.001), lower viral load (p = 0.001), higher rise in CD4 count (p = 0.017), lower incidence of tuberculosis (p = 0.001) and OIs (p = 0.001) at 6 months follow up, was observed among patients in the intervention group." (PMID 28520768, 2017). "Interestingly, CD4 T cells coexpressing IFN-γ and TNF-α and harboring a phenotype of effector-memory response were associated with active tuberculosis in HIV-uninfected and HIV-infected TB patients." (PMID 28759590, 2017). "Male gender, a CD4 count <350 cells/mm3, an unknown CD4 count, tuberculosis and renal failure were important predictors of a higher risk of IHM in our study." (PMID 28533849, 2017). "Hence, we analysed IL-7R mRNA transcripts of purified CD4+ T cells from tuberculosis patients and healthy contacts." (PMID 28582466, 2017). "In fact, tuberculosis is one of the opportunistic infection that occurs at any CD4 count in HIV patient, it might predicts clinical failure if it occurs after 6 months of initiation of ART which subsequently indicate the need of treatment change." (PMID 26889204, 2016). "Myeloid-derived suppressor cells have been detected in human tuberculosis and may be negatively correlated with CD4 and CD8 activation and function." (PMID 27228113, 2016). "Another study has demonstrated that PD-1-deficient mice have a large number of proliferating CD4+ T cells in their lungs, thus promoting tuberculosis rather than controlling it19." (PMID 27924827, 2016). "Therefore, initiating ART early should help decrease the risk of tuberculosis transmission and further contribute to tuberculosis control and IPT should be given even to patients who start ART at high CD4 counts." (PMID 27462361, 2016). "In some studies, where macrophages with a mutation in NRAMP1 protein were infected with mycobacteria, the ability to process antigens was loose, affecting the CD4 lymphocytes activity and therefore the Th1 response, promoting a Th2 profile and the progression of tuberculosis." (PMID 27830154, 2016). "This can be explained by the occurrence of tuberculosis across a wide range of CD4 counts, with less of a protective effect of early immune restoration, and because of the significant rate of unmasking immune reconstitution inflammatory syndrome (IRIS) in the first months after ART initiation." (PMID 26951573, 2016). "Moreover, recent clinical trials demonstrated a survival benefit in patients with HIV and tuberculosis with CD4 counts <50 cells/mm3 who initiate HAART early." (PMID 27271083, 2016). "Finally, in the many countries where HIV and tuberculosis are both highly prevalent, ART and IPT independently decrease the risk of tuberculosis in HIV-infected patients, even at high CD4 counts." (PMID 27462361, 2016). "Moreover, for patients who developed tuberculosis while in use of cART, we observed a per year increased protection of cART use, while controlling for CD4+ T lymphocyte count." (PMID 27001753, 2016). "In addition, POC implementation, POC testing for CD4 and tuberculosis, national EQA for malaria, guidelines for safety, a manual for sample collection, standard operating procedures for testing, and job aids, among others, were also developed." (PMID 28879127, 2016). "However, little data exists characterizing the production and regulation of IL-21-expressing CD4+ T cells during tuberculosis." (PMID 26785168, 2016).
tuberculosis (continued). "Work done by the Andersen group finds that cryptic epitopes of ESAT6 are minor components of natural immune response to M. tuberculosis but specific vaccination strategies that elicit CD4+ T cells specific for the subdominant epitopes generate more durable protection against tuberculosis." (PMID 25945999, 2015). "Mononuclear macrophages may present tuberculosis antigen to T cells (CD4+ and CD8+), activate the immune response to differing degrees, and induce the accumulation of T cells." (PMID 25780428, 2015). "Monthly income, age, history of tuberculosis treatment and current CD4 cell counts were not independently associated with reporting alcohol misuse." (PMID 25962171, 2015). "Requiring people co-infected with HIV and tuberculosis to stabilize on tuberculosis treatment before initiating ART may be beneficial only for patients with very low CD4 counts." (PMID 26170503, 2015). "In the multivariate analysis, being previously treated for tuberculosis (adjusted HR [aHR] 3.23, 95% CI 1.68 to 6.24), low albumin concentrations (aHR 0.74 per increase of 1 g/dL, 95% CI 0.58 to 0.95), and low CD4+ lymphocyte concentrations were independently associated with increased mortality." (PMID 26347376, 2015). "In order to assess the effectiveness of the Chinese government’s expanded access program, a cohort study on all adult HIV patients in Shenzhen was conducted from December 2003 to February 2014 to estimate the effects of antiretroviral therapy (ART) on mortality, tuberculosis and CD4 cell counts." (PMID 26213959, 2015). "But in contradiction to this study, a study done in Tanzania showed that not being on HAART, having CD4 % <25 %, having a history of tuberculosis and having hookworm infestation, were independent risk factors for anemia." (PMID 26413303, 2015). "Moreover, the incidence of active tuberculosis in HIV-infected individuals is inversely proportional to the number of CD4 T cells in their peripheral blood." (PMID 26018190, 2015). "In addition to this point justifying the commencement of HAART, patients' CD4 count should be monitored closely to know when to commence them on prophylaxes for opportunistic infections like pneumocystis carinii and tuberculosis." (PMID 26136407, 2015). "In our case, the patient’s initial CD4+ T cell counts were 55 cells/μL; this depletion of M. TB specific CD4+ T cells may contribute to reduced immune-response for tuberculosis in the lung." (PMID 25160905, 2014). "The cases with tuberculosis and HIV co-infection had a comparatively lower baseline CD4 count with a median count of 87 cells/mm3 compared to 220 cells/mm3 for the study population suggesting that the HIV was at an advanced stage in those with tuberculosis." (PMID 24695805, 2014). "Subjects with inactive tuberculosis evidence CD4+ central memory T-cell response." (PMID 24564297, 2014). "By contrast, patients with active tuberculosis evidence CD4+ effector memory T-cell responses." (PMID 24564297, 2014). "The probability of developing new opportunistic infections like tuberculosis is high if the baseline CD4 count is low which in turn might contribute to the poor rate of CD4 cells recovery." (PMID 25536416, 2014). "Finally, conventional Tfh (CD4+CCR5+) cells have been shown to mediate protective immunity against tuberculosis." (PMID 25343703, 2014). "Intradermal MVA85A, a candidate vaccine against tuberculosis, induces high amounts of Ag85A-specific CD4 T cells in adults who have already received the BCG vaccine, but aerosol delivery of this vaccine might offer immunological and logistical advantages." (PMID 25151225, 2014). "The expression of TLR-2 is already known to be induced on activated CD4+ T cells and is constitutively expressed on effector memory CD4+ T cell populations, in addition to effector cells derived from patients with persistent bacterial infections and tuberculosis." (PMID 24896098, 2014).
tuberculosis (continued). "Studies probing the CD4+ T cell response from individuals latently infected with Mtb or patients with active tuberculosis using either small or proteome-wide antigen screens so far revealed a multi-antigenic, yet mostly invariable repertoire of immunogenic Mtb proteins." (PMID 25157249, 2014). "Some showed that the expression ratio of Thl7 cells in tuberculosis patients didn’t vary significantly from those in the healthy, or it was even lower than in the healthy when accompanied by less expression of IL-6R of CD4 + T cells." (PMID 25089129, 2014). "Specific interventions that may have contributed to the decrease in tuberculosis incidence among persons with HIV during this period include raising the CD4 threshold for initiation on antiretroviral therapy and expanding HIV testing services." (PMID 24937804, 2014). "However, increases in CD4 counts vary by region, gender with a higher increase in CD4 count in women, the duration of antiretroviral therapy and on the co-existence of other infections, particularly tuberculosis." (PMID 24013838, 2013). "The frequency of PPD-specific CD4+ TNF-α-only-secreting T cells with an effector phenotype accurately distinguished active tuberculosis from latent tuberculosis infection with an area under the curve of 0.99, substantially more discriminatory than measurement of function alone." (PMID 23966657, 2013). "Persons diagnosed with tuberculosis were younger, more likely to be from Peru, have heterosexual sex as their HIV risk factor, have lower CD4+ lymphocyte count and higher HIV-1 RNA at ART initiation, and more likely to die than persons not diagnosed with tuberculosis." (PMID 24066096, 2013). "Furthermore, MDSCs from infected mice are capable of inducing activation and proliferation of CD4+ T cell cells and well as inhibiting proliferation showing a yet unidentified role for these cells in tuberculosis." (PMID 24224058, 2013). "Interestingly, a decrease in multifunctionality and a shift towards cytokine single-producing cells was recently shown to be a typical feature of antigen-specific CD4 T cells in patients with active tuberculosis." (PMID 24039703, 2013). "In models adjusted for sex, baseline CD4 count, age, treatment site, tuberculosis and year of ART initiation, KS patients were over three times more likely to have died at any time after ART initiation (hazard ratio[HR]: 3.62; 95% CI: 2.71–4.84) than those without KS." (PMID 23755122, 2013). "After controlling for the effects of gender, age, marital status, educational status, place of residence, HIV disclosure, history of tuberculosis treatment, CD4 cell count, WHO stage, and record of next appointment, five variables were found to be associated significantly with pre-ART LTFU." (PMID 24053770, 2013). "As findings from large prospective studies and clinical trials have demonstrated that delaying ART can result in increased overall mortality risk associated with AIDS, new guidelines recommend early ART initiation in patients with tuberculosis and severe CD4+ T-cell depletion." (PMID 23691062, 2013). "It is therefore possible that the functions of the antigen induced CD4+CD25hiFoxP3+ Treg cells in tuberculosis have similar regulatory function as the naturally occurring Treg cells and may be mediated by IL-4 expression." (PMID 23826366, 2013). "In a multivariate Cox proportional hazards model that adjusted for CD4+ lymphocytes and HIV-1 RNA, tuberculosis diagnosed after ART initiation was associated with an increased risk of death compared to tuberculosis diagnosis before ART initiation (HR 2.40; 95% CI 1.15, 5.02; P = 0.02)." (PMID 24066096, 2013). "CD4 counts less than 50cells/mm3 are associated with a higher risk of opportunistic illnesses such as Pneumocystis jirovecii pneumonia (PJP), cryptococcal meningitis, cytomegalovirus retinitis, central nervous system lymphoma and deaths from tuberculosis." (PMID 24312317, 2013).